KIT (KIT proto-oncogene, receptor tyrosine kinase)
Diseases named in the same sentence as KIT in open-access papers (continued):
Sharing a sentence is not in itself a finding about the gene and the disease.
mast cell tumors (continued). "In this work, we describe the use of RNAScope as a sensitive and specific method for the evaluation of c-KIT messenger RNA (mRNA) in canine mast cell tumor." (PMID 33665215, 2021). "Among other receptor tyrosine kinases, toceranib and masitinib both target the tyrosine kinase KIT, which has been frequently described as a prognostic marker and therapy target, especially in canine mast cell tumor." (PMID 34768937, 2021). "We investigated the expression of c-KIT mRNA with RNAscope in 60 canine mast cell tumors (MCTs), comparing it with the histological grade and KIT immunohistochemical expression patterns." (PMID 33665215, 2021). "Results showed that the greatest tumor response rates were seen in mast cell tumors (MCT) and that dogs with MCT possessing KIT mutations were much more likely to respond to therapy than those tumors with wild-type KIT." (PMID 32411603, 2020). "For this purpose, we used the HMC1.2 human mast cell leukemia and the C2 canine mast cell tumor cell line, which are two common models for the study of tyrosine kinase inhibitors and, in particular, the proto-oncogene KIT." (PMID 30459395, 2018). "Our research team evaluated double immunohistochemical expression of c-KIT/Ki67 in canine mast cell tumours and identified a strong correlation between the co-expression of c-KIT and Ki67 with survival time." (PMID 29207991, 2017). "Previously, we have demonstrated high number of c-KIT/Ki67 double-stained neoplastic cells in high-grade canine mast cell tumours." (PMID 29207991, 2017). "As such, increasing the dose of TOC would be a reasonable therapeutic approach to overcome KIT-overpexpressing TOC-resistant canine mast cell tumors." (PMID 24885200, 2014). "Notably, the drug also retains equivalent potency against wild-type KIT and the KIT V560G juxtamembrane domain mutant, underscoring its versatility across mast cell neoplasms." (PMID 40722727, 2025). "Examples include the use of a commercially available ISH assay for the detection of transcripts in FFPE tissue (RNAScopeTM) to evaluate KIT mRNA in canine mast cell tumours (n = 60), finding a statistically significant correlation between KIT mRNA expression and histological grade." (PMID 38473154, 2024). "An increase in the KIT gene copy number is often found in canine mast cell tumors." (PMID 38275618, 2024). "In conclusion, the aim of this study was to compare standard VP polychemotherapy and targeted therapy with IM in cases of mast cell tumors, and to investigate the associations between treatment response and factors that are known to impact MCT progression, such as histologic grade and KIT pattern." (PMID 35159380, 2022). "Interestingly, these deletion mutations are similar to those previously found in the juxtamembrane domain of c-KIT in canine cutaneous mast cell tumors in our laboratory and others." (PMID 20950418, 2010). "After the proposal of TOC for the treatment of canine mast cell tumors, several papers have investigated separately the expression of c-KIT, VEGFR-2, and PDGFR-β by IHC in different tumor subtypes (without clinical treatment) claiming that IHC expression could predict TOC therapy." (PMID 39126006, 2024). "Our results also demonstrated a correlation between c-KIT mRNA expression and histological grade, but further investigations are needed to confirm these findings that may potentially have an important significance for prognosis and treatment of canine mast cell tumor." (PMID 33665215, 2021). "In conclusion, the present study showed that AQ1 G4-binding compound inhibited KIT expression and its downstream signaling molecules GRB2, AKT and FYN in two in vitro models of human and canine mast cell neoplasms (HMC1.2 and C2 cells)." (PMID 30459395, 2018). "Mast cell tumours showing c-KIT I pattern presented few neoplastic mast cells with nuclear Ki67 and cytoplasmic c-KIT pattern." (PMID 29207991, 2017).
mast cell tumors (continued). "There are also case reports of a mast cell tumour in a llama, which exhibited positive membrane KIT expression, and a captive opossum (Didelphis virginiana), in which c-KIT positive cancerous cells were found to have spread to distant sites, including the liver, skin, kidney, pancreas and spleen." (PMID 30739231, 2019). "In this study, RNA-Seq was used to explore the effect of a G4-binding anthraquinone derivative, named AQ1, on the whole-transcriptome profiles of two common cell models for the study of KIT pathways; the human mast cell leukemia (HMC1.2) and the canine mast cell tumor (C2)." (PMID 30459395, 2018). "However, because TKI therapy for canine mast cell tumors does not result in a complete response in all cases, the response of GISTs to TKI therapy should be analyzed in the context of the KIT gene mutation profile." (PMID 40427321, 2025).
schwannoma (54 papers, 2007 to 2026). A benign, usually encapsulated slow growing tumor composed of Schwann cells. "Additionally, immunohistochemistry revealed strong positivity for S100 and SOX10, which is typical of schwannomas, and negative staining for markers like c-KIT, DOG1, and CD34, which are associated with GISTs." (PMID 40507589, 2025). "Studies with other RTK inhibitors that primarily target PDGFR and c-KIT (e.g., nilotinib, imatinib and sorafenib) showed that these RTK inhibitors exhibited strong anti-proliferative activity on primary human schwannoma and HEI-193 cells." (PMID 28427224, 2017). "Unlike GISTs, schwannomas typically do not express c-KIT (CD117) or DOG1, which aids in their differentiation from other submucosal tumors." (PMID 40115021, 2025). "In contrast to GISTs, schwannomas are consistently negative for CD117 (KIT) and usually negative for CD34, CKs, smooth muscle actin and desmin, but strongly positive for S100 protein and vimentin." (PMID 25360169, 2014). "c-KIT, CD34, and S-100 protein is negative in PAMT, which are usually positive in GIST, GIST and solitary fibrous tumor, and schwannoma and neurofibroma, respectively." (PMID 28103839, 2017).
acral melanomas (53 papers, 2009 to 2026). "BRAF and NRAS are the most commonly mutated oncogenes in acral melanomas, though they occur less frequently than in sun-exposed melanomas, while KIT mutations are more prevalent in ALM." (PMID 40362334, 2025). "Instead, mutations in the KIT gene and the predominance of acral lentiginous melanoma subtypes are more common, particularly in China and Japan." (PMID 40371294, 2025). "Among our four cases with KIT mutation (5% of prevalence), one was from a mucosal site, whereas the others were cutaneous tumors, one of which was classified as an acral melanoma." (PMID 39000050, 2024). "One example is for mucosal or acral melanomas, which occasionally exhibit a KIT mutation that provides a therapeutic target for imatinib." (PMID 39125519, 2024). "BRAF and NRAS mutations are common in acral melanocytic nevus, whereas acral melanoma shows lower rates of KIT, NF1, BRAF, and NRAS mutations and remarkable copy number variations in genes such as CCND1, CDK4, hTERT, PAK1, and GAB2." (PMID 35997352, 2022). "In Koreans, KIT mutations and increased KIT copy numbers are commonly observed in acral melanoma, and KIT mutations were found to be independent risk factors for a poor prognosis." (PMID 35997352, 2022). "Positive responses to KIT inhibitor treatment have been reported in cases of acral melanoma with KIT mutation." (PMID 35997352, 2022). "KIT mutations were detected exclusively in three acral lentiginous melanomas (10%); in one case it was found in association with a NF1 mutation and in another with a NRAS mutation." (PMID 33917086, 2021). "For example, in a case of acral melanoma with KIT mutation, targeting MET with a selective inhibitor successfully overcame resistance to KIT inhibition, as confirmed also in cell line studies." (PMID 32659961, 2020). "KIT mutations are often found in acral lentiginous melanoma (ALM) and mucosal melanoma (MuM), less frequently in LMM, and rarely in SSM and NM." (PMID 30214901, 2018). "In acral melanomas, several genomic aberrations, including amplification of 11q13 and KIT mutations, have been found." (PMID 21911917, 2011). "In another recent study, KIT mutations were identified in 23% of acral melanomas, 15.6% of mucosal melanomas, 1.7% of cutaneous melanomas, and none in choroidal melanomas." (PMID 20426858, 2010). "Furthermore, KIT mutations, frequently observed in acral melanomas, have been implicated in vitiligo pathogenesis, suggesting a potential shared molecular basis." (PMID 40861587, 2025). "Thus, while mechanical stress is broadly implicated in acral melanoma pathogenesis, its specific role in driving KIT mutations requires further investigation." (PMID 41301010, 2025). "Finally, mucosal and acral melanomas have been described to express KIT and to harbor activating KIT mutations." (PMID 24489649, 2014). "Mucosal and acral melanoma arising from sites such as the palms, soles and nail beds as well as cutaneous melanoma arising from chronically sun-damaged skin are forms of the disease with different but overlapping oncogenes and biologic behavior that have recently been found to harbor KIT mutations." (PMID 25609545, 2014). "Strikingly, the study of acral melanoma also identified recurrent driver mutations in RTK/RAS signaling genes, including PTPN11, KIT, NF1, KRAS, and NRAS, all of which are recurrent in human AML (and commonly associated with NPM1c mutations)." (PMID 40773291, 2025). "In acral melanoma, BRAF (9%), NRAS (17%), KRAS (8%), KIT (19%), and NF1 (7%) mutations were detected." (PMID 39564955, 2024). "Mutations in BRAF, NRAS, and KIT and amplifications of CCND1, CDK4, MITF, and TERT were well established in cases of acral melanoma." (PMID 36980308, 2023). "Human acral melanomas have also been studied at the genetic level, with mutations of BRAF (21.3%) and KIT genes (11.5%; 50% within exon 11) standing out." (PMID 35202309, 2022).
acral melanomas (continued). "In particular, several specific genomic aberrations including 11q13 amplification and KIT aberrations have been identified in acral melanomas." (PMID 21911917, 2011). "One of the first differences identified in AM in relation to non-acral melanomas was the increased prevalence of KIT mutations: mutated in 10% to 40% of AM in some series and in less than 10% of non-acral melanomas." (PMID 39616094, 2025). "For example, KIT inhibitors demonstrate some, but limited, utility for acral melanoma." (PMID 37444518, 2023). "Furthermore, a difference is also obvious between canine and human acral melanoma, in which BRAF and KIT mutations occur more frequently." (PMID 35202309, 2022). "Moreover, in c-KIT-mutant acral melanoma, the addition of TKIs targeting MET and KIT showed increased efficacy compared to KIT alone in the presence of hepatocyte growth factor, the ligand for MET." (PMID 33807778, 2021). "Another multicenter phase 2 trial in patients with metastatic mucosal or acral melanoma indicates an absence of significant difference between patients with or without KIT mutation." (PMID 33918490, 2021). "This KIT activation is intriguing, because it could be a direct target of therapies against acral melanomas using inhibitors targeting KIT (such as imatinib mesylate)." (PMID 21911917, 2011). "Interestingly, the key genomic alterations of acral melanomas described in a previous study (such as the highest proportion of triple-WT tumors, common KIT alterations, and lower frequencies of BRAF/RAS hotspot mutations) are consistent with the characteristics of the UV-low cluster in this study." (PMID 36246650, 2022). "The co-amplifications of the receptor tyrosine kinases KIT and PDGFRA on chromosome 4, as well as CDK4 on chromosome 12, are of particular interest for acral melanoma." (PMID 32825510, 2020). "There are several mutations occurring in acral melanoma that we did not identify in acral naevi, including NF1, KIT, and TERT promoter alterations, recently reported in 15%, 12%, and 11% of acral melanomas, respectively." (PMID 30995742, 2019). "Recurrent non-V600E BRAF, KIT, NF1, and TERT promoter mutations, present in acral melanoma, were not identified." (PMID 30995742, 2019). "In acral melanoma, BRAF and NRAS are still the most frequent mutations present (although less frequent than in non-acral cutaneous melanoma), followed by NF1 and KIT mutations." (PMID 30995742, 2019). "Considering we detected no recurrent non-V600E BRAF, KIT, or NF1 mutations in naevi, this may imply that acral melanomas harboring these mutations arise primarily de novo, whereas BRAF V600E or NRAS Q61 mutant acral melanomas may more frequently arise from pre-existing naevi." (PMID 30995742, 2019).
colorectal cancer (53 papers, 2006 to 2025). A primary or metastatic malignant neoplasm that affects the colon or rectum. "Loss of a WT allele or cnLOH were previously reported in GISTs with mutations in exon 9 of KIT, and cnLOH was described in a few series of breast, endometrial, and colorectal carcinomas." (PMID 25373456, 2014). "In a more recent study using a TMA comprising 137 patient-derived colon tumors and 179 associated serially passaged xenografts, it was found that c-KIT is expressed in approximately 50% of colorectal cancer tissues, in agreement with data collected from The Cancer Genome Atlas." (PMID 35490363, 2022). "Of these, two missense variants—2:32525512-32525512 (BIRC6) and 4:54727895-54727895 (KIT)—had been previously reported as mesothelioma and large intestine carcinoma." (PMID 37469410, 2023). "Analysis of the Cancer Genome Atlas Colorectal Cancer (COADREAD) RNA-Seq data set showed a significant positive relationship between KIT and SNAI2 mRNA expression (n = 380, Pearson r = 0.3704, p < 0.0001)." (PMID 36362141, 2022). "In our dataset, the N486D KIT variant was observed in bone cancer [DOID:184], rectum cancer [DOID:1993], colon cancer [DOID:219], and large intestine cancer [DOID:5672]." (PMID 29531238, 2018). "In the colorectal cancer set, KRAS (42.5%), PIK3CA (17.8%) and KIT (10.9%) were the most frequently mutated genes." (PMID 26968814, 2016). "Furthermore, it was recently demonstrated that c-KIT stimulates CSC properties in colorectal cancer cells, including CD44 expression and other stem cell markers." (PMID 35490363, 2022). "There have been no reports of KIT involvement in EGFRi responsiveness in the colorectal cancer literature, and the presence of these mutations in the responder group is of unknown significance." (PMID 26980732, 2016). "While it is clear that activating mutations in KIT are an early event in GISTs, it is not known whether they can serve as an initiating oncogenic event in colorectal cancer." (PMID 25197591, 2014). "Expression of c-KIT and SCF has been reported in patient-derived immortalized colorectal cancer cell lines and in premalignant and malignant colonic lesions, where c-KIT and SCF co-expression has been associated with a worse clinical outcome." (PMID 35490363, 2022). "Atoh1 was significantly elevated in colorectal cancer (CRC) cells stimulated by exogenous SCF or overexpressing c-KIT in vitro, while decreased by the blockage of SCF/c-KIT signaling with Imatinib." (PMID 29786668, 2018). "SCF has been reported as an effective delivery vector towards KIT-positive neuroblastomas and colorectal cancer cells with expression of wild-type KIT in vitro but has not been tested in mutant-KIT-driven malignancies." (PMID 35999600, 2022). "Less frequent mutations were seen in genes that are typically considered “druggable” but not seen previously in colorectal cancer including KIT, ERBB2 and ALK." (PMID 33632293, 2021). "It was reported that the treatment of refractory colorectal cancer with regorafenib, an inhibitor of multiple kinases, including vascular endothelial growth factor receptor (VEGFR) 1–3, Tie2, KIT, platelet derived growth factor receptor and RET, achieved a 6% partial response and 23% stable disease." (PMID 31769426, 2019). "Thus, the study of multiple regions of CMS4 colorectal cancers and the analysis of PDGFRA, PDGFRB, PDGFC and KIT showed the existence of a consistent intratumor heterogeneity." (PMID 29652830, 2018).